MTOR (mechanistic target of rapamycin kinase)
Diseases named in the same sentence as MTOR in open-access papers (continued):
Sharing a sentence is not in itself a finding about the gene and the disease.
lung cancer (continued). "However, in the presence of estradiol, PI3K/AKT/mTOR signaling pathway activation levels were higher in ERβ1/5-expressing lung cancer cells than those in ERβ1-expressing cells, suggesting that the interaction between ERβ1 and ERβ5 potentiated the effects of ERβ1 in non-genomic signaling." (PMID 33585221, 2020). "Interestingly, we found an activation of mTOR and its downstream target p70S6K in A549 lung cancer cells after LA exposure, suggesting that LA may suppress the autophagosome formation in a mTOR‐dependent manner." (PMID 32090494, 2020). "The present study suggests that the addition of SMI could increase the cytotoxicity of cisplatin by inhibition of the glycolysis metabolism through the AKT/mTOR/c-Myc pathway, which might provide a theoretical basis for the treatment of cisplatin-resistant nonsmall cell lung cancer." (PMID 32685545, 2020). "Thus, aberrantly-activated AKT/mTOR is a relevant therapeutic target in lung cancer." (PMID 32218702, 2020). "Thus, TIPE2 is observed to activate the Akt/mTOR signaling pathway, which might contribute to lung cancer pathogenesis." (PMID 31817720, 2019). "Hence, we next examined the activity of Akt/mTOR signaling pathway in lung cancer cells." (PMID 30755242, 2019). "The phosphatidylinositol-3-kinase (PI3K)/Akt/mTOR pathway is a commonly activated signaling pathway in cancer, which play an important role in drug resistance of cancers, including prostate cancer and lung cancer, while the relationships between Ishikawa and taxol is still unclear." (PMID 30175145, 2018). "Thus, inhibition of entire PI3K/AKT/mTOR pathway by auranofin could be a novel mechanism of action in auranofin-mediated anti-lung cancer therapy." (PMID 26657290, 2016). "However, LY294002 only inhibited p-Akt and p-mTOR, and rapamycin only inhibited p-mTOR, indicating that c-Met/PI3K/Akt/mTOR signaling is a key pathway that involved in the roles of HGF in lung cancer, and might be also the main target of curcumin." (PMID 27525306, 2016). "In addition, a recent work suggested that GA inactivates PI3K/Akt/mTOR in lung cancer cells." (PMID 27833555, 2016). "mTOR expression may be upregulated by numerous mechanisms in the pathogenesis of lung cancer." (PMID 25360163, 2014). "Furthermore, primary clinical trials of mTOR inhibitors have demonstrated that the inhibitors may be effective against lung carcinoma." (PMID 25360163, 2014). "Furthermore, the Akt/mTOR signaling pathway is frequently altered in certain types of cancer, including gastric cancer, prostate cancer, cervical carcinoma, renal cell carcinoma, lung carcinoma and pancreatic ductal adenocarcinoma." (PMID 25120661, 2014). "Importantly, CQ has been used to overcome resistance of lung carcinoma cells to different chemotheraputics such as the dual PI3K/mTOR inhibitor PI103 and crizotinib, while rapamycin has been administrated in a phase I trial of patients with advanced non-small cell lung cancer." (PMID 25078870, 2014). "Finally, the PI3K/AKT/mTOR pathway is recognized to play a central role in tobacco-induced carcinogenesis, and inhibitors of this pathway, including myoinositol and metformin, are promising agents for lung cancer prevention." (PMID 24216701, 2013). "It suggested that an activation of the EGFR/PI3K/AKT/mTOR pathway could be linked to CDKN2A homozygous deletion in lung cancer regardless of smoking status." (PMID 18549475, 2008).
lung cancer (continued). "It is possible that in EGFR mutant lung cancers there is already maximal activation of the PI3K/Akt/mTOR signalling pathway and thus an LKB1 mutation may not be required to further potentiate this signalling pathway." (PMID 18594528, 2008). "Our findings establish the potential of mitomet, especially when combined with mTOR inhibitors, for the prevention and treatment of LKB1 mutant lung cancer by targeting CSCs." (PMID 42138621, 2026). "Research has shown that SCP-1 has a significant growth-inhibitory effect on A549 lung cancer cells; it can arrest the cell cycle in the S phase; and it induced apoptosis in A549 cells through the Bax/Bcl-2 and PI3K/Akt/mTOR signaling pathways." (PMID 40507156, 2025). "Other piRNAs, including piR-55490, piR-46545, and piR-35127, have been downregulated in lung cancer and demonstrated tumor growth suppression by modulating the AKT/mTOR pathway." (PMID 40949873, 2025). "In lung cancer, PARP1 mediates the AMPK–mechanistic target of rapamycin (mTOR) pathway, which regulates autophagy induced by β‐hydroxybutyrate dehydrogenase 1 (BDH1)." (PMID 40904702, 2025). "Several downstream signaling pathways are often activated in various forms of lung cancer, including the PI3K/AKT/mTOR, MAPK/ERK, MEK/ERK, JAK/STAT, NF-κB, and transforming growth factor-beta (TGF-β) signaling pathways." (PMID 39991567, 2025). "ZnF3 from AC induces apoptosis in lung cancer cells and activates macrophages via the AKT/mTOR pathway." (PMID 40141325, 2025). "Key signaling pathways involved in the pathogenesis of lung cancer include RAF/MEK/ERK, PI3K/Akt/mTOR, and JAK/STAT signaling." (PMID 40149916, 2025). "In addition, it has been found that the PI3K/AKT/mTOR signaling pathway offers great possibilities for the treatment of lung cancer; however, targeted therapy acting on the PI3K/AKT/mTOR pathway may cause many side effects and deficiencies due to acquired drug resistance." (PMID 41155938, 2025). "Studies on lung cancer have also shown that TBK1 signaling was essential for the survival of KRAS-driven lung cancer cells, which is dependent on TBK1-AKT/mTOR signaling-mediated tumor growth and immunosuppression." (PMID 40076567, 2025). "In lung cancer, OTUB1 triggered lung cancer development by inhibiting RAS monoubiquitination; OTUB2 stabilized U2AF2 through the AKT/mTOR signaling pathway to promote the Warburg effect and tumorigenesis; and OTUD3 stabilized GRP78 to augment the malignancy." (PMID 40469292, 2025). "Our findings underscore the therapeutic potential of β-elemene in overcoming cisplatin resistance in lung cancer through the regulation of LINC00511 and the PI3K/AKT/mTOR pathway, offering new insights into treatment strategies for chemoresistant lung cancer." (PMID 41480385, 2025). "For instance, RASD1 suppresses cell growth in a lung cancer cell line and inhibits glioma invasion and migration by inactivating the AKT/mammalian target of rapamycin (mTOR) pathways." (PMID 40362656, 2025). "The combined treatment of Rosa canina extract and cisplatin significantly inhibited lung cancer cell proliferation by downregulating PARP-1 and the TLR2/MyD88/TRAF6/NF-κB signaling pathway, as well as the PI3K/Akt/mTOR pathway." (PMID 40022036, 2025). "Shikonin demonstrates synergistic effects when combined with the PI3K-Akt-mTOR inhibitor BEZ235, significantly reducing the viability of chemotherapy-resistant lung cancer cells." (PMID 40808675, 2025). "β-elemene overcomes cisplatin resistance in lung cancer by downregulating LINC00511 and inhibiting the PI3K/AKT/mTOR pathway." (PMID 41480385, 2025). "One study in nonsmall cell lung cancer demonstrated reduced phosphorylation of MAPK and PI3K/Akt/mTOR pathway targets, leading to strong inhibition and increased cell death." (PMID 40662801, 2025). "Lung cancer: In lung cancer, CCAT1/FABP5 promotes tumor progression through mediating fatty acid metabolism and stabilizing PI3K/AKT/mTOR signaling." (PMID 40717587, 2025).
lung cancer (continued). "In lung cancer, calcium/calmodulin-dependent protein kinase II (CAMK2) inhibitor 1 (CAMK2N1) is a tumour suppressor gene which acts through inhibition of the Akt/mTOR pathway." (PMID 40867253, 2025). "Specifically, it was demonstrated that BUB1 inhibition regulates AKT phosphorylation to modulate mTOR and ERK signaling pathways in lung carcinoma and osteosarcoma, respectively." (PMID 40723917, 2025). "In lung cancer specifically, gedatolisib (a dual inhibitor of PI3K and mTOR) is being tested in a phase I trial in combination with the CDK4/6 inhibitor palbociclib in NSCLC (NCT03065062)." (PMID 38339294, 2024). "In terms of angiogenesis and the epithelial–mesenchymal transition (EMT), both of which are critical events in lung cancer progression, curcumin has been found to inhibit both events through the suppression of the PI3K/Akt/mTOR pathway." (PMID 38672636, 2024). "Derived from exosomes of highly metastatic lung cancer cells, miR‐499a‐5p enhances EMT in LUAD by activating the mTOR signaling pathway." (PMID 39247621, 2024). "A large number of studies on lung cancer mainly focused on AKT/mTOR/NF-κB, EGFR-AKT-mTOR, and PI3K/ AKT/mTOR signal pathways." (PMID 38571356, 2024). "In lung cancer, piRNA-55490 can bind to the 3’-UTR of mammalian target of rapamycin (mTOR) mRNA leading to its degradation and resulting in the inhibition of cell proliferation." (PMID 38303021, 2024). "Our current study suggests that MH can potentially prevent the growth of lung cancer by downregulating MET and its downstream signaling markers, including p-mTOR, p-AKT, and NF-κB." (PMID 39518013, 2024). "The synergic activity of both FGFR and mTOR inhibitors has been demonstrated in cells harboring HNSCC, lung cancer, and HCC." (PMID 38255923, 2024). "It was found that exosome secretion in lung cancer is regulated by signaling pathway such as LKB1 and AMPK/mTOR, which can promote cell motility." (PMID 39247621, 2024). "It potentially promotes lung cancer progression, migration, and EMT processes through the PI3K/AKT/mTOR pathway and Hippo signaling pathway." (PMID 38711158, 2024). "In H460 lung cancer cells, gigantol was shown to destabilize tumor integrity via suppression of the PI3K/Akt/mTOR and JAK/STAT pathways at concentrations of 20–200 μM." (PMID 37568796, 2023). "In lung cancer, indeed, SOX2 activates AKT/mTOR signaling pathway, which in turn enhances the activity of the matrix-metalloproteinase-2 (MMP2)." (PMID 38096163, 2023). "Overexpressing miR-520a-3p suppresses proliferation, migration, and invasion and triggers apoptosis in lung cancer cells by inactivating AKT and downregulating mTOR, MMP2, and MMP9." (PMID 36835100, 2023). "Timosaponin AIII, as a glucosylated spirostane saponin of Anemarrhena asphodeloides (Asparagaceae) rhizomes, combated taxol-resistant lung cancer cells in vitro (2–8 μM) and in vivo (2.5 and 5 mg/Kg) via reducing PI3K/Akt/mTOR gene expressions." (PMID 36984763, 2023). "Since the mTOR-AKT pathway is a master regulator of autophagy, it is safe to say that SPHK1 promotes the invasion and migration of lung cancer cells simultaneously with (and possibly through) autophagy inhibition." (PMID 37190124, 2023). "In lung cancer, FRMD6 promoted the tumor growth and invasion via mTOR pathway, while FRMD6, as a tumor suppressor inhibited the carcinogenesis and progression of prostate cancer and glioma." (PMID 37280069, 2023). "Animal models have been developed to determine key molecular pathways involved in lung cancer, such as the PI3K/AKT/mTOR pathway and hypoxia-inducible factors, and test the efficacy of various therapies." (PMID 37371940, 2023). "miR-126-3p (miR-126) silencing upregulates apoptosis gene expression and inhibits the proliferation of lung cancer cells by upregulating p-PI3K and p-mTOR expression." (PMID 36835100, 2023). "In A549 lung cancer cells, fisetin has been shown to induce apoptosis, likely due to its ability to downregulate PI3K/Akt/mTOR signaling." (PMID 37568796, 2023).
lung cancer (continued). "Mechanistically, miR-199a-5p inhibits the expression of autophagy-related proteins by activating the PI3K/Akt/mTOR pathway, which promotes the development of MDR in lung cancer cells." (PMID 38169723, 2023). "In vitro, the ACK1 inhibitors (AIM-100 and Dasatinib) appeared to trigger adaptive autophagy-like response to protect lung cancer cells from apoptosis and activated the AMPK/mTOR signaling pathway, partially explaining its moderate antitumor efficacy." (PMID 36647009, 2023). "Akt/mTOR activation has been shown to enhance radioresistance in many kinds of tumors, including HNSCC, esophageal cancer, colorectal cancer, lung cancer, and brain cancer." (PMID 37940975, 2023). "In non‐small cell lung cancer, ZNRF2 upregulates mTOR protein expression to promote cell proliferation and inhibit cell apoptosis." (PMID 37551845, 2023). "Treatment of a mouse lung cancer model with indirubin‐3‐monoxime and TQ (5, 10, 10 mg/kg) significantly reduced the expression of Phospho‐Akt (p‐AKT), Phospho‐Mammalian target of rapamycin (p‐mTOR), Cas‐3, p‐53 and NF‐κB." (PMID 37697969, 2023). "Taken together, these results indicated that mTOR signaling is the upstream of USP5 and regulated the expression of USP5 in lung cancer." (PMID 37060095, 2023). "Among the 20E-down-regulated genes in lung cancer cells, several of them are considered to be oncogenes, including Notch3, HSF1, mTOR, SOX12, KLF16 (Kruppel-like factor 16,), and others." (PMID 37233697, 2023). "There have been increasing studies that have demonstrated the vital effect of necroptosis regulated by mTOR on a wide range of diseases, such as IBD, sepsis, lung cancer, and others." (PMID 38164133, 2023). "Auranofin, a rheumatoid arthritis drug, has been validated to repurpose application to trigger apoptosis and necroptosis in auranofin-sensitive lung cancer cells, accompanied by suppressing the PI3K/AKT/mTOR pathway." (PMID 36139919, 2022). "In lung cancer, miR-143 reduces the expression of hexokinase 2 (HK2) protein by targeting the mammalian target of rapamycin (mTOR) pathway." (PMID 35093153, 2022). "In this way, miR-206 regulates MET protein in A-549 lung cancer cells by directly targeting MET 3′-UTR and activated MET/PI3K/Akt/mTOR signaling pathway to induce DDP resistance (Chen QY." (PMID 35444536, 2022). "It has been found that several PI3K/Akt/mTOR targeted therapies such as pictilisib (PI3K inhibitor) and perifosine (Akt inhibitor) are undergoing clinical trials as treatments for lung cancer." (PMID 36500361, 2022). "RGZ suppresses the growth of lung cancer cells by upregulating the AMPK signaling-dependent pathway and downregulating the Akt/mTOR/p70S6K pathway." (PMID 36114448, 2022). "Fibulin2 (FBLN2) is decreased in the lung cancer cell lines, and the overexpression of FBLN2 would inhibit the activation of MAPK/ERK and AKT/mTOR signaling pathways, accompanied by the decreased migration and invasion of cells." (PMID 36033435, 2022). "PRMT5 exhibits FGFR3-dependent regulation through the activation of AKT, ERK, and mTOR, and the activated FGFR signaling pathway plays an important role in promoting lung cancer cell proliferation." (PMID 36364261, 2022). "mTOR kinase activation is substantially related to the surface expression of the tumor suppressor protein PD-L1 in human lung cancer cells, and the stimulation of the AKT/mTOR axis facilitates immune evasion through increased PD-L1 expression." (PMID 35682571, 2022). "Lung cancer cells were treated with 0–50 μM artonin F for 24 h, and the results showed that the ratios of PI3K, Akt, mTOR to GAPDH were reduced in cells treated with artonin F at the concentrations that induced apoptosis." (PMID 35631459, 2022). "Our studies in lung cancer cells and C. elegans are consistent with BMP signaling activating PI3K and downstream anabolic signaling pathways Akt and mTOR by BMPR2 Smad-independent mechanisms." (PMID 35641992, 2022).
lung cancer (continued). "Intriguingly, LOC554202 sustains both the Ras/Raf/MEK/ERK and PI3K/AKT/mTOR pathways by activating miR-31, indicating its potential as a promising therapeutic target for EGFR TKI-resistant lung cancer." (PMID 36139582, 2022). "In lung cancer, PI3K/AKT/mTOR signaling is a critical regulatory axis contributing to cell malignant phenotypes and drug resistance." (PMID 35535347, 2022). "We found that the majority of the DEGs were associated with cell growth pathways including cell cycle, inflammation pathways including mTOR and MAPK signaling, tumor pathways including melanoma and nonsmall cell lung cancer." (PMID 35941558, 2022). "Together, these results support a model that NOP56 downregulation induces a metabolic vulnerability to mTOR inhibition, which presents a new and rational strategy for treating KRAS-mutant lung cancer." (PMID 35039048, 2022). "If the features of LCNEC-null in our findings are proven, cases of this type of lung cancer should be redefined as pulmonary neuroendocrine tumours, with greater implementation of targeted therapy (PI3K/mTOR inhibitor)." (PMID 35144629, 2022). "In lung cancer, gefitinib and tripchlorolide induce lung cancer cell autophagy and apoptosis via blockade of the PI3K/AKT/mTOR pathway." (PMID 36430694, 2022). "Genetic alterations of EGFR, MAP2K1, mTOR, TEAD1, and YAP1 in The Cancer Genome Atlas (TCGA) cohorts of lung cancer occurred at respective frequencies of 15.0%, 1.80%, 6.00%, 1.80%, and 2.50%." (PMID 35655775, 2022). "Gefitinib and erlotinib inhibit the activation of EGFR-mediated PI3K/Akt/mTOR in A549, A549-gefitinib-resistant, KRAS-mutant H358, and H441 cells, leading to lung cancer cell apoptosis." (PMID 36547898, 2022). "Several inhibitors, including sirolimus (an mTOR inhibitor) and perifosine (a dual PI3K/AKT inhibitor), have entered the lung cancer clinical trial stage." (PMID 35529455, 2022). "In human lung cancer cell lines, acquired resistance to PI3K/mTOR inhibition was documented after increased glycolysis associated with mitochondrial DNA mutations." (PMID 33107222, 2021). "In bladder and lung cancer, inhibition of PI3K/Akt/mTOR significantly inhibits migration and tumorigenesis while increasing apoptosis via downregulation of Bcl-2 proteins." (PMID 34316328, 2021). "Dual inhibition of Erk and PI3K/mTOR with LY3214996 and LY3023414 inhibitors respectively, has been tolerable and resulted in synergistic inhibition on tumor growth in RAS-driven lung cancer." (PMID 34946644, 2021). "AKT and mTOR were demonstrated to be critical cell signaling pathways for CSC maintenance in many cancers, including lung cancer." (PMID 33530617, 2021). "Researchers also found that clearing-heat TCM decoctions or active ingredients from clearing-heat herbs can inhibit the growth of lung cancer via RAS/RAF/ERK pathway and the PI3K/AKT/mTOR pathway." (PMID 34646330, 2021). "LncRNA UCA1 has been demonstrated to promote EMT and mediates acquired resistance to gefitinib in lung cancer cells through MAPK/ERK, AKT/mTOR, and STAT3 signaling pathways." (PMID 33931980, 2021). "For instance, piR-55490 inhibits lung cancer cells and tumor proliferation by binding to the 3′ UTR of mTOR mRNA and degrading its targeted mTOR mRNA." (PMID 34249688, 2021). "Anti-cancer drug Gigantol is found to target CSC via suppression of the PI3K/AKT/mTOR and JAK/STAT pathway in lung cancer cells." (PMID 33573362, 2021). "These analyses indicate that two key regulators of the mTOR pathway, STK11 and PTEN, have different functions in lung cancer biology and that KRAS and PTEN are mutually exclusive." (PMID 33652656, 2021). "The treatment of the cell-permeable leucine derivative promoted AKT/mTOR phosphorylation and reversed the inhibitory effect of JPH203 in the reduction of CSC activity in pemetrexed-resistant lung cancer cells." (PMID 34681614, 2021).